MTOR (mechanistic target of rapamycin kinase)
Diseases named in the same sentence as MTOR in open-access papers (continued):
Sharing a sentence is not in itself a finding about the gene and the disease.
cerebral malaria (3 papers, 2015 to 2020). A sequestration of Plasmodium falciparum in the brain, which can cause coma and/or seizures. "In regard to infections caused by protozoan parasites, augmented mTOR-sensitive translation was associated with parasite persistence during Toxoplasma gondii infection in macrophages whereas eIF4A inhibition suppressed progression of cerebral malaria." (PMID 32479529, 2020). "Together these studies support the mTOR pathway as a potential target for adjunctive therapeutic strategies in cerebral malaria treatment." (PMID 29162126, 2017). "For instance, it has been shown that inhibition of mTOR signaling by treating Plasmodium berghei ANKA-infected mice with mTOR inhibitor rapamycin prevented pathology in an experimental cerebral malaria." (PMID 26587536, 2015).
cerebral palsy (3 papers, 2020 to 2024). A group of disorders affecting the development of movement and posture, often accompanied by disturbances of sensation, perception, cognition, and behavior. "Inhibition of mTOR has been shown to prevent neuroinflammation in a mouse model of cerebral palsy, indicating its potential therapeutic effect in this condition." (PMID 38564092, 2024). "In a mouse model of cerebral palsy, mTOR inhibitor rapamycin prevented neuroinflammation and neuronal cell death." (PMID 34515928, 2021). "Autophagy is known to be regulated by mTOR, rapamycin's mammalian target, and mTOR inhibition has been found to prevent neuroinflammation in a mouse model of cerebral palsy." (PMID 32655767, 2020).
chronic allograft nephropathy (3 papers, 2014 to 2023). "It impaired lymphocyte activation and proliferation by inhibiting mTOR and also prevents chronic allograft nephropathy (CAN) by inhibiting the proliferation of vascular smooth muscle cells with little to no nephrotoxicity." (PMID 38105889, 2023). "For the 2 patients who had chronic allograft nephropathy in the mTOR inhibitor group, 1 patient already had eGFR less than 30ml/min/1.73m2 during conversion while the other patient had graft failure 5 years after conversion to mTOR inihibitor." (PMID 28160552, 2017). "On the other hand, 5 patients had graft failure (2 due to chronic allograft nephropathy and 3 due to unknown causes) in the mTOR inhibitor group and 11 patients lost their grafts (1 due to acute antibody-mediated rejection and 10 had chronic allograft nephropathy) in the non-conversion group." (PMID 28160552, 2017).
Chronic colitis (3 papers, 2020 to 2025). A chronic inflammatory disease of the large intestine (colon, cecum and rectum). "In conclusion, the results of our study demonstrate that monotropein has a therapeutic effect on chronic colitis and can inhibit the transformation of chronic colitis into fibrosis by regulating autophagy via the mTOR/P70S6K pathway." (PMID 40041493, 2025). "Monotropein inhibited TGF-β1-induced EMT in IEC-6 cells, inhibited the phosphorylation of mTOR and its downstream proteins, and increased the autophagy activity in chronic colitis mice and IEC-6 cells." (PMID 40041493, 2025). "DSS-induced chronic colitis increasedthe p-Akt/Akt and p-mTOR/mTOR ratios (∼1.39 times and 11.51%, p < 0.05) and decreased the p-AMPK/AMPK ratio (90.1%, p < 0.05) compared to normal animals." (PMID 38222654, 2024).
Conjunctival melanoma (3 papers, 2022 to 2025). "In patients with conjunctival melanoma, which involves dysregulation of the MAPK and PI3K/AKT/mTOR pathways, mutations in BRAF, NRAS, and NF1 are commonly observed, while KIT and PTEN mutations occur less frequently." (PMID 41001300, 2025). "Since alterations of several components of the MAP kinases, PI3K/mTOR, and cell cycle pathways have been reported in conjunctival melanoma, we decided to assess the sensitivity of conjunctival melanoma to targeted inhibition mostly of kinase inhibitors." (PMID 35326726, 2022). "In tumoral tissues of conjunctival melanomas, we and others have previously reported the activation of Mitogen-Activated Protein Kinase (MAPK) and possibly phosphoinositide 3-kinase (PI3k)/mTOR pathways." (PMID 35326726, 2022).
crescentic glomerulonephritis (3 papers, 2018 to 2020). A histopathologic term for a pattern of diseases characterized by extensive crescent formation in the glomeruli; patients present clinically with rapid deterioration of renal function, and possible progression to end-stage renal failure within weeks or months. "However little is known about the role of glomerular mTOR activity in crescentic glomerulonephritis." (PMID 31658846, 2019).
cryptosporidiosis (3 papers, 2023 to 2025). Intestinal infection with organisms of the genus Cryptosporidium. "Recent studies have reported the induction of autophagy in intestinal epithelial cells via mTOR inactivation during Cryptosporidium infection of Caco-2 cells." (PMID 39040107, 2024). "C. parvum-induced mTOR-dependent autophagy is shown to modulate host cell processes related to pathophysiology of cryptosporidiosis." (PMID 36999034, 2023).
delirium (3 papers, 2016 to 2022). A disorder characterized by confusion; inattentiveness; disorientation; illusions; hallucinations; agitation; and in some instances autonomic nervous system overactivity. "It is possible that these effects by metformin on inflammation and pathways involving AMPK and mTOR can decrease delirium risk and prolong patient’s life, although evidence for these effects in humans are limited." (PMID 36399107, 2022).
dengue (3 papers, 2018 to 2025). "In this study, we describe a role for host mTORC2 in dengue replication, demonstrating that dengue can interact with cellular mTOR signaling, activating mTORC2 and, as a result, promoting cell survival and efficient viral replication." (PMID 36171757, 2022). "The observation that mTORC2 is required for efficient dengue replication raises the possibility of mTOR as a target for host-directed antiviral therapeutic development." (PMID 36171757, 2022). "The importance of mTORC1 in dengue replication is supported by studies demonstrating increased viral replication in the response to pharmacologic mTOR inhibition and a recent study implicating mTORC1 in the dengue-induced activation of lipophagy." (PMID 36171757, 2022). "Taken together, these results indicate that niclosamide confers anti-mTOR activity, but the anti-dengue activity of niclosamide is mediated through a mTOR-independent pathway." (PMID 30125275, 2018). "Intriguingly, less raptor protein associated mTOR in dengue-infected cells, whereas rictor was not impacted." (PMID 36171757, 2022). "However, mTOR dysregulation in myeloid cells is found in diverse infections, ranging from HIV99,100,101 to dengue." (PMID 40177636, 2025). "As expected, NS5 was immunopurified in the mTOR pulldown in dengue-infected cells, but absent in the IgG immunoprecipitation control." (PMID 36171757, 2022). "Quantitative proteomics [I-DIRT; Isotopic Differentiation of Interactions as Random or Targeted], designed to identify bona fide dengue-host protein-protein interactions, defined a high-confidence protein interaction network including a predicted interaction between the dengue NS5 protein and mTOR." (PMID 36171757, 2022).
Dravet syndrome (3 papers, 2019 to 2025). "Precise treatment strategies based on molecular mechanisms have achieved breakthroughs: mTOR inhibitors significantly reduce seizure frequency in TSC patients, and cannabidiol (CBD) demonstrates broad-spectrum antiepileptic efficacy in TSC and Dravet syndrome." (PMID 40979205, 2025). "Furthermore, mTOR hyperactivation accompanies epileptic activity across different seizure models including animal models of TLE, PTE, FCDII, Dravet syndrome, ASD, and TSC." (PMID 35923547, 2022).
edema (3 papers, 2020 to 2025). An abnormal accumulation of fluid beneath the skin, or in one or more cavities of the body. "This suggests that the PI3/Akt/mTOR signaling pathway may be involved in hypoxia induced lung edema." (PMID 32508639, 2020). "Thus, inhibition of PI3K/AKT/mTOR/HIF-1α/VEGF signaling pathway could reduce the injuries of ALI such as exaggerated inflammatory response and pulmonary edema." (PMID 34183011, 2021).
embryonal carcinoma (3 papers, 2015 to 2020). A non-seminomatous malignant germ cell tumor characterized by the presence of large germ cells with abundant cytoplasm resembling epithelial cells, geographic necrosis, high mitotic activity, and pseudoglandular and pseudopapillary structures formation. "In line with this hypothesis, genetic PHGDH knockdown promoted mTOR-independent autophagy in embryonal carcinoma stem-like cells." (PMID 32138178, 2020).
endometrioid carcinoma (3 papers, 2010 to 2026). "In in vitro studies, cells with PTEN inactivation in endometrioid carcinoma are sensitive to mTOR inhibitors, since the loss of PTEN leads to constitutive activation of downstream components, which in turn up-regulates mTOR activity." (PMID 20368795, 2010).
endometrioid endometrial carcinoma (3 papers, 2016 to 2021). "For example, downregulation of miR-199b with increased mTOR was observed in endometrioid endometrial carcinoma." (PMID 27145368, 2016).
enterocolitis (3 papers, 2022 to 2025). An inflammatory process affecting the small intestine and colon. "RIP3, which accumulates in reactive astrocytes in response to spinal cord injury, has also been shown to be associated with mTOR in enterocolitis." (PMID 39893345, 2025).
enteropathy (3 papers, 2019 to 2023). "mTOR inhibition is attractive given the high response rate of lymphoproliferation, enteropathy, and AIC, possibly explained by the hyperactivation of mTOR signaling downstream of Akt, which is enhanced by increased PI3K activity." (PMID 38022498, 2023).
eosinophilia (3 papers, 2018 to 2023). "All these data demonstrated that mTOR impairment in myeloid cells increased eosinophilia, which consequently resulted in elevated airway inflammation in response to allergen challenge." (PMID 29720621, 2018). "Unbiased single-cell sequencing analysis of controls and SP-CI73T mutants at a time coordinated with peak eosinophilia (14 days) defined heightened inflammatory activation, chemotaxis, and survival signaling (IL-6, IL-4/13, STAT3, Glucocorticoid Receptor, mTOR, and MYC) in eosinophils." (PMID 35571100, 2022).
erectile dysfunction (3 papers, 2021 to 2023). Persistent or recurrent inability to achieve or to maintain an erection during sexual activity. "A previous study has demonstrated that the NF-κB, PI3K–AKT, and mTOR signaling pathways are overrepresented in DM-induced erectile dysfunction." (PMID 38034011, 2023). "The objective of this study was to determine if mTOR is an activator of NADPH oxidase in the penis and to determine the functional relevance of this pathway in a translationally relevant model of diet-induced erectile dysfunction." (PMID 35052748, 2021).
Fibrofolliculoma (3 papers, 2014 to 2022). Fibrofolliculoma is a clinically asymptomatic, 2-4 mm, skin-colored, dome-shaped smooth papule. "However, responses in humans to mTOR inhibitors, namely for fibrofolliculomas, were not seen, suggesting that alternative oncogenic pathways exist beyond mTOR activation in FLCN-deficient tumors." (PMID 36421797, 2022).
food allergy (3 papers, 2018 to 2023). Gastrointestinal disturbances, skin eruptions, or shock due to allergic reactions to allergens in food. "Our analysis of the epigenetically regulated transcriptional response points to gene networks activated via E2F and MYC, and mTOR metabolic programs as markedly altered in children with food allergy and delineates these as key pathways modified by gene–environment interactions." (PMID 30120223, 2018). "Lactobacillus paracasei PC-01 inhibits the activation of the mammalian target of rapamycin (mTOR) signaling pathway by amino acids in mammalian intestinal epithelial cells, alleviates the pro-food allergic response to amino acids, and consequently provides relief from a food allergy." (PMID 36770908, 2023).
gallbladder adenocarcinoma (3 papers, 2017 to 2023). A carcinoma that arises from glandular epithelial cells of the gall bladder. "Survival analysis in a study by Leal indicated that high p-mTOR expression is associated with poor prognosis in patients with advanced gallbladder adenocarcinoma." (PMID 28114374, 2017). "Compared to other gallbladder adenocarcinoma without HCG, the proportion of M1 macrophage was at a higher level and the gene sets of MYC targets v1 and PI3K/AKT/mTOR signaling were highly expressed in our case." (PMID 37841278, 2023).
Graves disease (3 papers, 2022 to 2023). Graves' disease is an autoimmune disorder that leads to overactivity of the thyroid gland (hyperthyroidism).It is caused by an abnormal immune system response that causes the thyroid gland to produce too much thyroid hormones. "Moreover, Graves’ disease is considered as the consequence of a breakdown in TSHR tolerance, and selected cleavage TSHR antibody could produce a robust effect on the MAPK/PI3K-AKT/mTOR/S6K signaling cascades, the maintenance of which determined the thyroid cell fate of death." (PMID 35846879, 2022).
hyperinsulinemic hypoglycemia (3 papers, 2015 to 2025). An inherited autosomal recessive syndrome characterized by the disorganized formation of new islets in the pancreas and congenital hyperinsulinism. "The mammalian target of rapamycin (mTOR) inhibitor, sirolimus, has been used in hyperinsulinemic hypoglycemia which was unresponsive to other medical treatment." (PMID 32157856, 2020). "The mammalian target of rapamicin (mTOR) inhibitor, sirolimus, has been used in hyperinsulinemic hypoglycemia that was unresponsive to other medical treatment." (PMID 32157856, 2020). "Furthermore, the mammalian target of rapamycin (mTor) inhibitor sirolimus has recently been proven successful in four infants with severe hyperinsulinemic hypoglycemia unresponsive to diazoxide." (PMID 26608306, 2015).
hyperplasia (3 papers, 2022 to 2025). An abnormal increase in the number of cells in an organ or a tissue with consequent enlargement. "Studies have implicated tamoxifen in the pathogenesis of endometrial hyperplasia and carcinoma via activation of the mTOR pathway, suggesting that targeting the mTOR pathway could mitigate tamoxifen-induced endometrial proliferation." (PMID 39819881, 2025). "Moreover, mTOR activation was higher in CD compared to reactive lymphoid hyperplasia (used as a control group)." (PMID 35655778, 2022).
hypertensive heart disease (3 papers, 2014 to 2023). Abnormal enlargement of the heart resulting from long-standing hypertension. "In hypertensive heart disease, factor-alpha-related protein 9 (CTRP9) decreased phosphorylation levels of phosphatidylinositol 3-kinase (PI3K), protein kinase B (Akt), and mammalian target of rapamycin (mTOR) proteins, which led to reduced vascular endothelial cell injury." (PMID 37405054, 2023).
Hyponatremia (3 papers, 2022 to 2024). An abnormally decreased sodium concentration in the blood. "In mRCC patients treated with vascular endothelium growth factor (VEGF)- and mammalian target of rapamycin (mTOR)-targeted agents, hyponatremia has been correlated with a worse prognosis." (PMID 36052244, 2022).
hypospadias (3 papers, 2023 to 2024). Hypospadias is the displacement of the urethral meatus on the ventrum of the penis. "A recent study using a chemical-induced rat hypospadias model suggested that decreased mTOR activity is associated with hypospadias, possibly through increased autophagy." (PMID 36712925, 2023). "In the genital tubercle of rats with hypospadias, the expressions of Akt, mTOR and S6 were reduced, while p-PERK, p-eIF2α and ATF4 proteins’ expressions increased." (PMID 39728417, 2024). "Meanwhile, some direct or indirect inhibitory proteins of the autophagy pathway (e.g., p-Akt, p-mTOR and p-S6) were also significantly decreased in the GT of hypospadias fetuses, suggesting that DBP might enhance autophagy by inhibiting the PI3K/Akt/mTOR pathway." (PMID 39698037, 2024).
hypothyroidism (3 papers, 2017 to 2026). Abnormally low levels of thyroid hormone. "Thus, additional works are required to explore the mTOR-independent mechanisms underlying hypothyroidism-reduced GLUT1 expression." (PMID 28322267, 2017). "This is supported by the increased phosphorylation of serine 757 inhibiting autophagy through the mechanistic target of rapamycin (mTOR) in hypothyroidism." (PMID 39301315, 2024).
idiopathic membranous nephropathy (3 papers, 2021 to 2023). "In idiopathic membranous nephropathy, sPLA2-IB and PLA2R cause podocyte injury by activating the p38MAPK/mTOR/ULK1 signaling pathway that is mediated by insufficient autophagy." (PMID 34721589, 2021). "Rapamycin, the selective inhibitor of mTOR protein kinase, was proved to reduce podocyte apoptosis by inhibiting the mTOR/P70S6K/4EBP1 signaling pathway and activating podocyte autophagy in idiopathic membranous nephropathy (IMN) mice model." (PMID 34881244, 2021).
immune thrombocytopenia (3 papers, 2021 to 2025). "PTEN inhibits the PI3K/Akt/mTOR pathway and mediates the autophagy of platelets and is a characteristic feature of an autoimmune disorder known as immune thrombocytopenia (ITP)." (PMID 40148800, 2025). "For example, alpha-interferon can induce severe immune thrombocytopenia in those suffering from chronic hepatitis C. Moreover, probiotics that modulate the mTOR/PI3K/Akt signaling pathway can activate immune responses." (PMID 35996406, 2022).
infantile hemangiomas (3 papers, 2022 to 2026). "The last decade has been marked by the use of highly efficacious beta‐blockers for infantile hemangiomas (IHs) and by the growing interest of mammalian target of rapamycin (mTOR) inhibitors in various aggressive vascular anomalies with slow‐flow and/or partial lymphatic differentiation." (PMID 35668029, 2022).
intracranial aneurysm (3 papers, 2022 to 2025). "Our human data clearly showed increased molecular aging, elevated oxidative stress, and the activation of aging and inflammation‐associated pathways NF‐κB and mTOR in intracranial aneurysm tissue compared to non‐diseased control vessels." (PMID 41026146, 2025). "Of note, by regulating the mTOR signaling pathway, circRNAs have been implicated in the formation of intracranial aneurysms." (PMID 36505409, 2022). "As the core of the pathway–pathway interaction network, mTOR signaling is also associated with genes related to intracranial aneurysms." (PMID 36505409, 2022). "Moreover, it shows augmented oxidative stress and enhanced activation of aging and inflammation‐associated pathways mTOR and NF‐κB in the intracranial aneurysm tissue." (PMID 41026146, 2025). "This study provides the first direct evidence of accelerated molecular aging in human intracranial aneurysm tissue, marked by telomere shortening, oxidative DNA damage, and activation of mTOR and NF‐κB pathways." (PMID 41026146, 2025). "Additionally, intracranial aneurysm tissue presented higher activation of mTOR and NF‐κB pathways, which are known to contribute to inflammation and aging." (PMID 41026146, 2025). "Moreover, activation of the mTOR pathway and increased vascular endothelial apoptosis in KS and ADPKD could affect the intracranial aneurysm growth in our patient." (PMID 35327948, 2022).
invasive lobular breast carcinoma (3 papers, 2021 to 2024). An infiltrating lobular adenocarcinoma of the breast. "The mTOR signalling pathway was significantly involved in the progression of Invasive Lobular Carcinoma (ILC)." (PMID 34573857, 2021). "Similarly, CDH1 and PIK3CA have been commonly identified in invasive lobular breast carcinoma, but whether these concurrent mutations are sensitive to PI3K/Akt/mTOR agents remains to be confirmed." (PMID 33723724, 2021).